UCHL5 (ubiquitin C-terminal hydrolase L5)
Diseases named in the same sentence as UCHL5 in open-access papers (continued):
Sharing a sentence is not in itself a finding about the gene and the disease.
renal carcinoma (1 paper, 2024). A carcinoma arising from the epithelium of the renal parenchyma or the renal pelvis. "Therefore, the relevance, especially the sufficient association, of UCHL5 as a renal cancer marker requires further investigation." (PMID 39034372, 2024). "We would like to further investigate TA derivatives in the inhibition of renal cancer to clarify the potential of UCHL5 as a biomarker and drug target in following study." (PMID 39034372, 2024). "A significant finding is the increased abundance of UCHL5 in the blood of patients with renal cancer, rising from 18 to 100 ng/L, suggesting its potential as a potential prognostic marker for future therapy." (PMID 39034372, 2024). "The other reports also emphasized the importance of UCHL5 in regulating renal cancer metabolic and cell cycle process." (PMID 39034372, 2024). "Notably, we found that the increase of UCHL5 expression in renal cancer cells decreases the antigen processing and presentation of RCC tumor-infiltrating B cells." (PMID 39034372, 2024). "In renal cancer IHC samples, the infiltration of immune cells in the RCC tumor was also observed expression of UCHL5, similar to that of UCHL3." (PMID 39034372, 2024).
renal cell carcinoma (1 paper, 2024). "Further research identified that the expression of UCHL5 in RCC tumors is correlated with transport proteins, which led us to find that the abundance of UCHL5 in the blood of late-stage renal cell cancer patients is upregulated from 18 ng/L to 500 ng/L." (PMID 39034372, 2024). "Therefore, we propose that the abundance of UCHL5 in patients' blood can be a possible indicator of poor prognosis for renal cell cancer." (PMID 39034372, 2024).
serous carcinoma (1 paper, 2019).
serous ovarian cancers (1 paper, 2019). "Subsequent genomic analyses of 600 human high-grade serous ovarian cancers in The Cancer Genomics Atlas (TCGA) revealed UCHL5 gene-containing amplicons across chromosome 1q31.1–1q31.2." (PMID 31666925, 2019).
urothelial carcinoma (1 paper, 2022). A malignant neoplasm derived from the transitional epithelium of the urinary tract (urinary bladder, ureter, urethra, or renal pelvis). "In urothelial carcinoma, the UCHL5 inhibitor b-AP15 increases protein polyubiquitination and endoplasmic reticulum (ER) stress, further inhibiting cancer stem cells and overcoming cisplatin resistance." (PMID 36428630, 2022).
viral infection (1 paper, 2021). "Our study indicates that UCHL5 is also important for NLRP3 activation during viral infection." (PMID 34431717, 2021).
cancer (43 papers, 2014 to 2025). A tumor composed of atypical neoplastic, often pleomorphic cells that invade other tissues. "As one of the isomers of UCHs, UCHL5 participates in the ubiquitination regulation of various proteins and is associated with the occurrence and development of several malignant tumors." (PMID 32351584, 2020). "Proteasome-associated UCHL5 is a negative regulator of proteasome activity, as established in both human cancer cell-lines and the nematode C. elegans." (PMID 29474458, 2018). "Recently, we have reported that the anti-cancer activity of copper (II) pyrithione CuPT and gold (I) complex auranofin is tightly associated with their ability to target and inhibit the 19S proteasome-associated deubiquitinases (DUBs), UCHL5 and USP14." (PMID 26097878, 2015). "Recently, we have reported that the anti-cancer activity of copper (II) pyrithione CuPT and gold (I) complex auranofin is associated with targeting the 19S proteasome-associated deubiquitinases (DUBs), UCHL5 and USP14." (PMID 26097878, 2015). "Previous research has shown that targeted inhibition of TA attenuates UCHL5 polyubiquitination catalysis in cancer cells." (PMID 39034372, 2024). "Proteasome subunit hRpn13 is partially proteolyzed in certain cancer cell types to generate hRpn13Pru by degradation of its UCHL5/Uch37-binding DEUBAD domain and retention of an intact proteasome- and ubiquitin-binding Pru domain." (PMID 38509117, 2024). "In this study, we discovered that UCHL5 plays a negative regulator role in Wnt signaling in various cancer cells." (PMID 35256667, 2022). "The findings show substantially elevated UCHL5 expression in the cancer tissue relative to adjacent bladder tissue." (PMID 36428630, 2022). "In this study, we found that increased expression of the proteasomal deubiquitinase USP14 and UCHL5 in primary cancer cells from CML patients compared to healthy donors." (PMID 36082692, 2022). "Proteasomal deubiquitinases (USP14 and UCHL5) have fundamental roles in the ubiquitin‐proteasome system and possess multiple functions during cancer progression." (PMID 36082692, 2022). "Overexpression of UCHL5 enhances, while silencing of UCHL5 represses, cancer cell proliferation and migration by c-Myc, SLC25A19, and ICAM5 transformation via AKT/mTOR pathways." (PMID 36428630, 2022). "Several types of cancers are sensitized to cell death by depleting or pharmacological inhibition of UCHL5/USP14." (PMID 33919439, 2021). "In vivo b-AP15 prevents tumor progression in four different solid tumor models, including HNSCC, indicating deubiquitinating activity of UCH37/UCHL5 represents a novel therapeutic target for cancer." (PMID 33585209, 2020). "b-AP15, a selective small molecule inhibitor of proteasomal USP14 and UCHL5 deubiquitinases (DUBs), has shown selectivity and efficacy in several other types of cancer cells." (PMID 31694672, 2019). "In cancer and healthy tissues both the expression level and subcellular location of UCHL5 vary greatly." (PMID 29474458, 2018). "Recently, a novel small molecule b-AP15 is identified as an inhibitor of the USP14/UCHL5 (DUBs) of the 19S proteasome, resulting in cell growth inhibition and apoptosis in several human cancer cell lines." (PMID 28968984, 2017). "Selective inhibition of USP14 and UCHL5 by b-AP15 or auranofin has been developed as a promising strategy against some carcinomas." (PMID 28619062, 2017). "We have recently demonstrated that Aur mainly targets proteasome-associated UCHL5 and USP14 and thereby induces proteasome inhibition, caspase activation and apoptosis in several cancer cell lines." (PMID 26625200, 2016). "Furthermore, DUB inhibitors targeting USP14 and UCHL5 downregulate ERα expression and induce cancer cell apoptosis, providing a prospective strategy for ER-positive BCa treatment." (PMID 38177530, 2024).
cancer (continued). "It is worth noting that given the universal function of UCHL5 in regulating tumorigenesis, the upregulation of UCHL5 in the blood may also be related to other cancers." (PMID 39034372, 2024). "UCHL5 knockdown suppressed cancer cell growth even though it promoted Wnt signal activity." (PMID 35256667, 2022). "Moreover, the role of UCHL5 in the regulation of cancer cell proliferation and migration has already been reported." (PMID 36428630, 2022). "In various cancers, the expression of UCHL5 and USP14 is upregulated." (PMID 33919439, 2021). "Additionally, previous research believed that nuclear or cytoplasmic UCHL5 expression, respectively, was reported to be a predictor for survival in several cancers." (PMID 32596150, 2020). "For elderly patients with reduced proteostasis capacity, high UCHL5 levels may further inhibit proteasome activity, thereby promoting apoptosis in cancer cells." (PMID 29474458, 2018). "Overexpression of USP14 or UCHL5 was observed in several carcinomas." (PMID 28619062, 2017). "Among these DUBs, POH1, UCHL5 and USP14 are associated with the 19S proteasome; they are often overexpressed in several carcinoma cells, which renders them potentially new therapeutic targets in these cancer cells." (PMID 26625200, 2016). "Similarly, since the expression of UCHL5 is correlated with various types of tumors, it is a valuable topic to determine whether UCHL5 can be a common marker for cancer screening." (PMID 39034372, 2024). "A recent article found that PTIR1 binds to the C-terminal of UCHL5 and activates its ubiquitination function, thereby inhibiting immune proteasome activity and limiting the processing and presentation of neoantigens, then preventing T cells from recognizing and attacking cancer." (PMID 39034372, 2024). "However, despite the negative effect of UCHL5 on Wnt signaling pathway in cancer cells, we failed to observe more aggressive cancer progression caused by hyperactivation of Wnt signaling pathway under the UCHL5-depleted condition." (PMID 35256667, 2022). "UCHL5 could stabilize the seven-pass transmembrane receptor Smoothened (Smo) protein via deubiquitination and further activated the Hedgehog (Hh) signaling pathway to maintain tissue homeostasis of cancers." (PMID 32351584, 2020). "In addition to RPN11, UCHL5 and USP14 are also associated with cellsurvival and cancer progession." (PMID 24977961, 2014). "USP14 and UCHL5, members of the DUB family, have been observed to be upregulated in various cancers, playing significant roles in tumor progression." (PMID 40804247, 2025). "In these cancers, USP14 and UCHL5 have been shown to stabilize crucial oncogenic proteins and promote tumor progression." (PMID 40804247, 2025). "UCH37 (also known as UCHL5), a proteasomal DUB, plays roles in protein degradation, DNA repair, and transcription and is overexpressed in several cancers." (PMID 40832226, 2025). "USP43, USP52, JOSD1, UCHL5 and OTUB1 all reduced levels of the HIF-1α target CA9 in the secondary validation screen in two different non-cancer cell lines." (PMID 39009674, 2024). "Next, we focused on Smad1, which is thought to promote the invasive and metastatic potential of certain types of cancer, and examined the expression level of Smad1 in JEG-3 and HTR-8/SVneo cells under UCHL5 inhibition." (PMID 37762005, 2023). "Although the knockdown effect of UCHL5 on the promotion of cancer activity is hidden by proteotoxic stress, the effect of the DIX ubiquitination antagonized by UCHL5 on Wnt-related cancers should be examined in a future study." (PMID 35256667, 2022). "In drug-resistant cancer cells, inhibitors of UCHL5 and USP14 mitigate resistance and sensitize cancer cells to cell death by modulating diverse cellular mechanisms." (PMID 33919439, 2021).
cancer (continued). "Considering the potential value of UCHL5/NFRKB in cancer, we analyzed the expression of UCHL5 and NFRKB in GC through the TCGA database and qPCR, whose results demonstrated that UCHL5 and NFRKB were up-regulated in GC." (PMID 32351584, 2020). "Proteasome–ubiquitin receptor hRpn13/Adrm1 binds and activates deubiquitinatingenzyme Uch37/UCHL5 and is targeted by bis-benzylidine piperidone RA190, whichrestricts cancer growth in mice xenografts." (PMID 28598414, 2017). "Our previous reports have shown that PtPT induces accumulation of Ub-prs due to inhibition of UCHL-5 and USP14 in other cancer cells." (PMID 28619062, 2017). "The inhibitors targeting DUBs as novel anti-cancer therapies have been developed, such as both WP1130 and b-AP15 against UCHL5." (PMID 24465953, 2014). "Ubiquitin carboxyl-terminal hydrolase L5 (UCHL5), as one of the isomers of carboxyl-terminal hydrolase of ubiquitin, participates in ubiquitination regulation of proteins and plays a crucial role in a variety of malignant tumors." (PMID 39068672, 2024). "For example, UCHL5/USP14 suppresses apoptosis and autophagic cell death to promote cancer." (PMID 33919439, 2021). "UCHL5 (or UCH37), USP14 and POU1 (Rpn11) are the three DUBs of the 19S proteasome that have been massively investigated and targeted due to their great potency on cancer cells." (PMID 32272746, 2020). "Additionally, bAP15, a depressor of the 19S proteasome DUBs (UCHL5 and USP14), exhibits significant inhibition of cell growth and invasion in several human cancers." (PMID 32596150, 2020). "Since we have identified that the bio-target of ZnPT involves USP14 and UCHL5, whether overexpression of USP14 or UCHL5 could add resistance of cancer cells to ZnPT should be investigated in the future." (PMID 28086217, 2017). "Interestingly, examination of gene expression profiles of different cancer cell lines (Broad-Novartis Cancer Cell Line Data Base) showed that USP14 and UCHL5 are both strongly expressed in MM cells." (PMID 27264969, 2016). "Gene expression profiling of other cancer cell lines reveal common statistically significant differences in proteostasis in ALDH+ CSCs compared to the bulk of the tumor cells, including reduced levels of Hsp70 and/or Hsp90 in CSCs defined by ALDH, together with reduced levels of UCHL5 mRNA." (PMID 40597978, 2025). "However, in HepG2 cancer cells, either UCHL5 or USP14 knockdown did not abrogate CuPT-mediated ubiquitinated protein accumulation." (PMID 24912524, 2014).
tumor (41 papers, 2010 to 2026). "Another inhibitor, VXL1570, also inhibits the functions of USP14 and UCHL5, which when used alone caused tumor reduction in Waldenstrom's macroglobulinemia tumor-bearing mice." (PMID 39759114, 2025). "A proteasome inhibitor, b-AP15, that targets 19S regulatory particle associated DUBs, including USP14 and UCHL5, showed anti-tumor activity." (PMID 33158118, 2020). "Positive cytoplasmic UCHL5 tumor immunoexpression is linked to increased survival of patients with small (<5 cm) tumors (p = 0.001), disease stages I-II (p = 0.025), and age 66 years or older (p = 0.037)." (PMID 29474458, 2018). "It is possible that excess UCHL5 expression substantially impairs proteasome activity, causing abnormal accumulation of proteasomal substrates, and harming tumor cells." (PMID 29474458, 2018). "In stages I-II of the disease, small (<5 cm) tumor size, or age 66 or older, UCHL5 positivity was linked to better prognosis, when compared to patients with negative tumor immunoexpression." (PMID 29474458, 2018). "We investigated the association of cytoplasmic UCHL5 tumor expression to assess clinicopathological parameters and patient survival." (PMID 29474458, 2018). "According to recent studies, b-AP15 and VLX1570 could also be a potential therapy for leukemia and WM by inhibiting 19S proteasome-associated DUBs such as USP14/UCHL5 and inducing tumor-cell apoptosis." (PMID 32354135, 2020). "UCHL5 knockout markedly accelerated cell proliferation and xenograft tumor growth, while its overexpression suppressed both." (PMID 42037453, 2026). "We discovered that protein modification-related, including HDGF, SIRT-7, UBE2A, and UCHL5, elevated expression in tumor tissues." (PMID 40041484, 2025). "The capacity of tumor cells to proliferate dramatically diminished in comparison to the control group when UCHL5 was knocked down." (PMID 38773433, 2024). "And the expression of UCHL5 in RCC tumor cells increased B cells infiltration, suggesting an immunosuppressive correlation with B cells but not with T cells." (PMID 39034372, 2024). "and UCHL5 stably expressed OS-RC-2 were implanted in mice dorsum, and separated tumor bulk after three weeks." (PMID 39034372, 2024). "First, we discovered that UCHL5 stimulates the Wnt/β-catenin pathway in tumor cells to enhance glycolysis." (PMID 38773433, 2024). "USP14, RPN11, and UCHL5 are three major regulatory DUBs of 26S proteasome, and their inhibitors also affect tumor development." (PMID 37190313, 2023). "B-AP15 (a USP14 and UCHL5 inhibitor) inhibits tumor growth in solid tumor models of squamous cell carcinoma, lung cancer, breast cancer, and colorectal cancer in vivo." (PMID 37190313, 2023). "Upregulation of the TGF signaling pathway is the main mechanism by which UCHL5 modulates malignant tumor progression." (PMID 37497216, 2023). "Abnormalities of the ubiquitin-proteasome system are key in PAAD pathogenesis, and the ubiquitin-proteasome UCHL5 can promote tumor progression and dry expression depending on involvement of the ELK3 protein." (PMID 37396042, 2023). "In our study, UCHL5 downregulation significantly suppressed both tumor growth in vivo and cell proliferation and migration in vitro." (PMID 36428630, 2022). "b‐AP15, an inhibitor of USP14 and UCHL5, exhibited potent tumour‐killing activity in BCR‐ABLWT and BCR‐ABLT315I CML cell lines, as well as in CML xenografts and primary CML cells." (PMID 36082692, 2022). "We also found that UCHL5 downregulation significantly suppressed both tumor growth in vivo and cell proliferation and migration in vitro." (PMID 36428630, 2022). "We compared UCHL5 mRNA expression in normal and tumor tissues of NSCLC patients using TCGA database." (PMID 33046988, 2020). "Accumulating evidence indicates that UCHL5 plays an important role in tumorigenesis, tumor invasion and migration 12-16." (PMID 33046988, 2020). "The relative UCHL5 expression level significantly increased in EC tissues compared with non-tumor specimens." (PMID 32596150, 2020).